IL37 (interleukin 37)
Diseases named in the same sentence as IL37 in open-access papers (continued):
Sharing a sentence is not in itself a finding about the gene and the disease.
cancer (67 papers, 2011 to 2026). A tumor composed of atypical neoplastic, often pleomorphic cells that invade other tissues. "A novel immune regulator is interleukin-37 (IL-37), already shown to be involved in the inflammation associated with the pathophysiology of many human disorders, including cancer." (PMID 37298214, 2023). "Regarding the remaining genes that exhibit an IL-37-correlated expression pattern, there is evidence for their association with the development of human cancers and for their potential to serve as disease biomarkers." (PMID 36551790, 2022). "Due to its potent effect for inhibiting innate and adaptive immune responses, our recent publication revealed that IL-37 was also closely associated with cancer development such as oral squamous cell carcinoma, colorectal cancer, and hepatocellular carcinoma." (PMID 35935954, 2022). "Among these are proteins associated with inflammation (i.e., interleukin-37), physiological responses such as electrolyte secretion (i.e., calcium-activated chloride channel regulator 4), and cancers such as cutaneous T cell lymphoma (i.e., melanoma inhibitory activity protein 2)." (PMID 38947182, 2024). "HCC is a typical inflammation-related cancer, and genetic variations within the IL-37 gene may be associated with the risk of HBV infection." (PMID 31073186, 2019). "Moreover, IL-37 treatment conferred a cancer-specific immunity to previously susceptible mice upon treatment with rIL-37 such that they failed to succumb to a re-challenge despite increases in inoculum size of active malignant cells." (PMID 29641433, 2018). "Therefore, IL-37 has the ability to suppress innate and acquired immunity of the host, and effectively control inflammatory stimulation, which was considered as a new hallmark of cancer." (PMID 37928545, 2023). "Interleukin-37 (IL-37) is a cytokine primarily known for its anti-inflammatory properties, but its role in cancer pathogenesis reveals a complex and multifaceted influence." (PMID 42238575, 2026). "The dual nature of IL-37's influence underscores its potential as both a therapeutic target and a biomarker for cancer progression, which remain to be validated in prospective clinical studies." (PMID 42238575, 2026). "Data derived from other cancers suggest that the best indicator of IL-37 activity is likely to be the level of the IL-37 in cancer tissue as a function of severity/survival." (PMID 39206201, 2024). "While there is a growing body of evidence highlighting the involvement of IL37 in various diseases, including cancer, its specific role in OSCC has remained unclear." (PMID 39500733, 2024). "IL-37 is a relatively recently discovered cytokine, with its most biologically active isoform being IL-37b, and it has been studied in cancers where it appears to have a protective role." (PMID 38337827, 2024). "IL-37 has been shown to enhance the polarization of M1 macrophages, which in turn promotes anti-cancer activity." (PMID 38312834, 2024). "Recent studies have shown significantly lower levels of IL-37 in peripheral blood mononuclear cells from HCC patients compared to non-cancer cohorts, indicating a reduction in M1 TAMs." (PMID 38312834, 2024). "In this review, we draw on recent advances to provide update on the biological characteristics of IL-37 and its clinical potential as immunological regulator, therapeutic targets as well as disease modifiers in cancer." (PMID 37928545, 2023). "Exogenous IL-37 was proved to repress the proliferation and migration of cancer cells directly through β-catenin suppression both in vitro (DLD1 and HT-29 cells) and in animal models of colorectal cancer (CRC) in vivo." (PMID 37928545, 2023). "In this study, we aimed at the investigation of the possible prognostic potential of IL-37 in patients with cancer utilizing bioinformatics tools and publicly available databases." (PMID 36551790, 2022).
cancer (continued). "Our findings highlight the role of IL-37 in harnessing antitumor immunity by inactivation of cytotoxic T cells and establish a new defined inhibitory factor IL-37/SIGIRR in cancer-immunity cycle as therapeutic targets in CRC." (PMID 35046386, 2022). "On the other hand, the ratio of IL-18-to-IL-37 levels was higher in the serum and PBMCs of patients with oral squamous cell carcinoma (OSCC) compared to non-cancer individuals and associated with shorter OS and DFS." (PMID 36551790, 2022). "Non-cancer individuals can be effectively distinguished from the OSCC patients by the ratio of serum IL-18/IL-37 (cut off value: 2.15)." (PMID 34248996, 2021). "Given its ability to suppress the production of inflammatory factors, it is unsurprising that the majority of studies investigating the role of IL-37 in cancer have shown that IL-37 is decreased in cancer, with low levels associated with poor prognosis." (PMID 31231372, 2019). "According to research by the cancer center in University of Colorado, IL-37 exerts its anti-inflammatory actions through regulation of dendritic cells (DCs)." (PMID 29641433, 2018). "Compared with the nontumoral IL‐37 density in epithelial cells, the intratumoral IL‐37 expression in cancer cells was reduced (P < 0.0001)." (PMID 30004182, 2018). "Compared with the control group, the effects of IL-37 on cell proliferation, migration, invasion, apoptosis and cancer stem cells were abolished in β-catenin overexpressing cells." (PMID 28467774, 2017). "Further studies will be necessary to properly evaluate the implications of IL-37 and IL-1R8 interaction in cancer biology." (PMID 28533483, 2017). "Recently, it has been revealed that altered expression of IL-37 contribute to the initiation and progression of cancer." (PMID 27835881, 2016). "Interleukin 37 (IL-37) has been reported to play a significant role in innate immune response and to be involved in several kinds of cancers." (PMID 27225603, 2016). "However, IL-37 can also act as a common contributor to cancer and chronic infection immunosuppression." (PMID 41293155, 2025). "Studies have highlighted the significance of IL-37 in various cancer contexts." (PMID 40444012, 2025). "Similarly, in non-small cell lung cancer (NSCLC), IL-37 secreted by cancer cells drives this polarisation." (PMID 40547518, 2025). "Moreover, IL-37 expression correlates with cancer invasion and prognosis, further supporting its involvement in tumorigenesis." (PMID 40191189, 2025). "IL-37 has been studied in chronic autoimmune diseases and cancers." (PMID 38337827, 2024). "However, the detailed data within the literature are very variable, as some studies investigated circulating IL-37, while others have measured cancer vs normal tissue levels of IL-37." (PMID 39206201, 2024). "The differential role of IL-37 in the GI tract and among different cancers may be due to the host differential immunological response(s) to various challenges, with different outcomes." (PMID 39206201, 2024). "In contrast to other members of the IL-1 family, far less is currently understood concerning the role of IL-37 in cancer, it may be related to the fact that its murine or chimpanzee homologue has not yet been discovered." (PMID 37928545, 2023). "Interestingly, the expression of IL-37 genes behaved inhibiting cancer cells proliferation and advancing apoptosis only after the transplantation of a NSCLC cell line (H1299) into nude mice, but not in IL-37- transfected H1299 cell lines." (PMID 37928545, 2023). "In addition, our data strengthen the understanding of IL‐37 and emphasizes the important role of IL‐37 in cancer." (PMID 36891351, 2023). "Especially in recent decades, the frontiers of IL-37 exploration are ever-increasing and include work on its involvement in the pathogenesis of human diseases but also its specific expression patterns in certain conditions, including cancer." (PMID 37298214, 2023).
cancer (continued). "In addition, IL-37 reportedly exerts tumor-inhibiting effects in a variety of cancers, such as breast, cervical, melanoma, and non-small cell lung cancer; refer to the relevant review for details." (PMID 35741608, 2022). "Finally, analysis using the STRING database processing data from the various depositories revealed that protein molecules involved in the IL-37 signaling pathway are also members of cancer-related pathways." (PMID 36551790, 2022). "Notably, the pathophysiology of IL-37 can be understood from certain chronic infections and cancer, because they evade the immune response through host anti-inflammatory and immunosuppressive mechanisms." (PMID 34248996, 2021). "Thirdly, the pathogenesis of different tumors is varied and IL-37 may be a double-edged sword that has multiple roles in different phase and different cancer types." (PMID 32226541, 2020). "While most studies investigating a role for IL-37 in cancer have determined that IL-37 is an anti-tumorigenic cytokine, some studies have suggested that IL-37 may also have pro-tumorigenic functions." (PMID 31231372, 2019). "Inflammation is one of the characteristics of cancer, indicating that IL-37 might inhibit cancer development through inflammation pathway suppression." (PMID 28467774, 2017). "MRNA levels of IL-37 in cancer tissues were lower when compared with corresponding normal tissues." (PMID 26791086, 2016). "Interestingly, IL-37 has been shown to exert protective effects in various cancer types." (PMID 39206201, 2024). "Importantly, recent research indicates that IL-37 could serve as a novel therapeutic tool for cancer patients, and there is growing evidence suggesting its potential role as a prognostic marker across various human cancers." (PMID 39206201, 2024). "Importantly, latest studies also showed that IL-37 may be a novel therapeutic target for cancer monitoring." (PMID 37928545, 2023). "Furthermore, IL-37 can exert an inhibitory effect on cancer development and progression." (PMID 34248996, 2021). "Thus, the potential use of IL-37 as a novel therapeutic target may be beneficial in the modulation of the inflammatory, metabolic and immune response as well as cancer development." (PMID 34248996, 2021). "Therefore, IL-37 may serve as a potential key factor in restoring inflammatory balance in cancer development and treatment." (PMID 33489865, 2020). "In contrast, far less is currently understood concerning the role of more recently identified members of this family in cancer such as IL-33 and IL-37, although such data that is available also indicates that these may have both pro- and anti- tumorigenic effects." (PMID 31231372, 2019). "However, it is important to understand whether IL-37 is a friend or foe of cancer." (PMID 41596472, 2026). "This supports the notion that IL-37 plays a hepato-protective role during HCC development by influencing the immune response and promoting an anti-cancer environment." (PMID 38312834, 2024). "In-depth study on the mechanism and key aspects of IL-37-mediated immune response may provide the theoretical basis for further clarifying the occurrence and development of immune response and further elucidating the pathogenesis of immune-related diseases and carcinomas." (PMID 29805973, 2018). "Moreover, the CTC-induced inflammation is the main mechanism underlying the promoting effect of CTCs on the metastatic colonization of disseminated carcinoma cells, since inhibiting the inflammatory response with IL-37 could efficiently suppress the effect of CTCs." (PMID 28415700, 2017). "While no reports currently exist on targeting IL-37 and/or IL-38 in human cancer therapy, concerns remain regarding the potential for long-term antibody treatment to lead to unintended immune suppression or autoimmunity." (PMID 40191189, 2025). "While IL-37 does not affect the proliferation and colonisation of cancer cells, it suppresses the migration and invasion ability of endometrial cancer cells." (PMID 37296736, 2023).
cancer (continued). "IL-37 shows a negative effect on cancer cell proliferation and invasion through the STAT3 signaling pathway." (PMID 36237303, 2022). "Our study has raised the intriguing possibility that IL-37 may be involved in many major biological processes regulated by TGF-β, such as cancer, fibrosis, tissue repair and inflammation." (PMID 28733640, 2017). "The identification of IL-37 and its crosstalk within different oncogenic pathways in HCC progression may help in a better understanding of therapeutic strategy for HCC or other cancers." (PMID 27835881, 2016). "In conclusion, the results of this study have highlighted the function of IL-37 in harnessing antitumor immunity through the inactivation of cytotoxic T cells and established a newly defined suppressor IL-37/SIGIRR as a treatment option for CRC in the cancer immune cycle." (PMID 37927605, 2023). "Oestrogen and progesterone do not have an effect on the IL-37 protein in cancer cells." (PMID 37296736, 2023). "IL-37 exerts a negative effect on cancer cell proliferation and invasion through STAT3 signaling." (PMID 36237303, 2022). "Since the activity of IL-37 lies mainly in the suppression of proinflammatory signaling factors such as mTOR, AKT, and PI3K, all involved in autophagy and key metabolic functions of immune and cancer cells, we further processed individual correlations with genes in these processes." (PMID 36551790, 2022). "HCC is a typical inflammation-related cancer caused by hepatitis B and C virus (HBV/HCV), aflatoxin exposure or alcoholism in extreme cases, the absence of active IL-37 protein may be a factor of increased risk for HCC progression in chronic HBV infected patients." (PMID 37928545, 2023).
infection (33 papers, 2008 to 2026). The state of being infected such as from the introduction of a foreign agent such as serum, vaccine, antigenic substance or organism. "Treatment with interleukin‐37 (IL‐37), an anti‐inflammatory factor, has unique anti‐inflammatory and antiviral effects on infections caused by various pathogens." (PMID 40452816, 2025). "However, as no studies have been reported on the association between IL-37 and SARS-CoV, this section focuses on the role of IL-37 in infections caused by MERS-CoV and SARS-CoV-2." (PMID 41293155, 2025). "But IL-37 also may lead to increased infection and mortality in infection caused by some pathogens possibly due to its inhibitory effects on immune response." (PMID 29805973, 2018). "In total, IL37 could be beneficial in the control of SIV infection by decreasing the inflammation associated with a strong virus replication in the acute phase of the infection." (PMID 31138840, 2019). "Understanding IL-37 and immune regulation is key to developing strategies that protect against excessive inflammation during infection." (PMID 41293155, 2025). "In this study, we investigated the effect of IL‐37 treatment on the SARS‐CoV‐2 Omicron‐infection induced inflammatory response and its molecular mechanism." (PMID 40452816, 2025). "To further validate the anti‐inflammatory effect of IL‐37 administration on M1 macrophages during SARS‐CoV‐2 Omicron infection, we induced the differentiation of mouse bone marrow (BM)‐derived cells into M1 macrophages in vitro." (PMID 40452816, 2025). "IL-37, for example, is a key anti-inflammatory cytokine with the potential to limit excessive immune activation during infection." (PMID 40431327, 2025). "The model mice exhibited a continuous decrease in weight for 3 days after BA.5 or BF.7 infection, and then the weights of the BA.5+IL‐37 and BF.7+IL‐37 mice began to rebound at 3 dpi." (PMID 40452816, 2025). "Interleukin 37 (IL-37) plays a crucial regulatory role in infection and immunity, inhibits innate and adaptive immunity as an anti-inflammatory cytokine by inhibiting proinflammatory mediators and pathways." (PMID 37024713, 2023). "The results of a Western blot assay indicated that VV-IL-37-GFP infection increased IL-37 protein expression in HCC mice." (PMID 36146619, 2022). "The results showed that the number and ratio of M2 macrophages in liver granulomas were significantly higher in the CPP-IgG2Fc-IL-37 group than in the other two IL-37 groups and the infection groups." (PMID 36002836, 2022). "On the other hand, IL-37 reverses the immunometabolic changes and histone post-translational modifications in monocytes, thereby inhibiting cytokine production after infection." (PMID 34248996, 2021). "For the further endpoints of interest, associations were observed in all patients for IL37 rs2723186 with CMV disease, for IL10 rs1800872 with the occurrence of graft loss or death, and for IL10 rs3024496 with the occurrence of infections." (PMID 33861738, 2021). "IL-33 is released in response to tissue damage, and IL-33 release is induced by IL-37 (cathelicidin), which has a protective function against UTIs since its release is significantly decreased in epithelial cells after infection with UPEC." (PMID 34835359, 2021). "In a mouse model of infection with Streptococcus pneumoniae, the data showed that an initial intervention with IL‐37 was detrimental to the prevention of S. pneumoniae infection, which promoted the bacteremic spread and increased mortality." (PMID 30414292, 2019). "Although the results showed a higher expression of IL‐37 in infected connective tissue, we considered the extent of the infection to be a more important factor." (PMID 30414292, 2019). "IL-37 decreased tissue damage during infection, a finding suggesting that regulation of inflammatory cell recruitment is essential to maintain normal tissue function." (PMID 25375146, 2014).